AQP2 (aquaporin 2)
Diseases named in the same sentence as AQP2 in open-access papers (continued):
Sharing a sentence is not in itself a finding about the gene and the disease.
nephrotic syndrome (9 papers, 2008 to 2025). A collection of symptoms that include severe edema, proteinuria, and hypoalbuminemia; it is indicative of renal dysfunction. "Consistent with this, PAN-induced nephrotic syndrome is associated with a marked downregulation of AQP2 expression in the collecting duct." (PMID 25165480, 2014). "The results demonstrate that PAN-induced nephrotic syndrome is associated with decreased urine concentration, manifested by an increased urine output, decreased urine osmolality, and a marked upregulation of collecting duct water channels (AQP2)." (PMID 25165480, 2014). "The results showed that the serum levels of cholesterol, triglyceride, TNF-α, and IL-6 in rats with nephrotic syndrome were increased and the gene and protein expressions of AQP2 and AVP were up-regulated in rats with adriamycin injected into caudal vein." (PMID 36678585, 2023). "The escape has been observed in the proteinuria phase of experimental models of nephrotic syndrome, and one mechanism for this escape includes a vasopressin-independent decrease in AQP2 in the collecting ducts." (PMID 32560242, 2020). "Aquaporin-2 (AQP2), a vasopressin-regulated water channel protein, is known to be selectively excreted into the urine through exosomes (UE-AQP2), and its renal expression is decreased in nephrotic syndrome." (PMID 32560242, 2020). "In conclusion, the first implication of this study in rats with PAN-induced nephrotic syndrome is that the beneficial effect of WPC on water balance occurs via an inhibitory effect on PAN-induced AQP2 expression." (PMID 25165480, 2014). "Our results show that WPC improves nephrotic syndrome, including proteinuria and ascites, through inhibition of AQP2 and ENaC expression." (PMID 25165480, 2014). "In this study, it was found that, in rats with PAN-induced nephrotic syndrome, there were increases in the expression of AQP2 and urine output, whereas WPC significantly inhibited AQP2 trafficking, but urine output remained increased." (PMID 25165480, 2014). "Reduced abundance of inner medullary AQP2 has been reported in various rodent models of nephrotic syndrome." (PMID 23349960, 2013). "The study shows the precise localization of AQP2 and AVRP2 in canine kidneys, as well as the low expression of AQP2 and AVRP2 in nephrotic syndrome." (PMID 34903939, 2021). "Further study is required to measure urinary antidiuretic hormone excretion relating to the inhibition of AQP2 expression and alleviation of kidney damage by WPC treatment in nephrotic syndrome." (PMID 25165480, 2014). "The therapeutic effect of AR on nephrotic syndrome (NS) may be demonstrated by reducing the expressions of arginine vasopressin (AVP) mRNA, AVP V2 receptor mRNA, and AVP-dependent aquaporin-2 (AQP2) mRNA, thereby eliminating edema." (PMID 35924053, 2022). "Furthermore, in models of nephrotic syndrome induced by either PAN or adriamycin, decreased expression of renal AQP2 has been observed." (PMID 32560242, 2020). "There is a marked downregulation of both AQP2 and AQP3 expression, which could be a physiologic response to extracellular water reabsorption in patients with nephrotic syndrome." (PMID 20142913, 2008). "In the previous study, Poria cocos Wolf (Chinese Pinyin: Fu Ling, WPC) markedly inhibited AQP2 expression in response to hypertonic stress in vitro; however, the possible benefits and mechanism of this have not been fully elucidated in nephrotic syndrome animal models." (PMID 25165480, 2014).
Ureteral obstruction (9 papers, 2010 to 2024). Obstruction of the flow of urine through the ureter. "In mice with lithium induced nephrogenic diabetes or unilateral ureteral obstruction, models that are associated with reduced AQP2 kidney expression, renin inhibition for 7 days has been demonstrated to increase AQP2 expression." (PMID 37565514, 2023). "The vasopressin escape and ureteral obstruction represent two pathophysiological states with the loss of the Aqp2 gene expression associated with the induced epithelial-to-mesenchymal transition of the collecting duct principal cells." (PMID 35685285, 2022). "RAS activation also plays a role in the downregulation of AQP2 protein expression associated with ureteral obstruction." (PMID 31572210, 2019). "Either bilateral or monolateral sustained ureteral obstruction is associated with persistently decreased AQP2 mRNA and protein levels in the inner medullary collecting ducts 95,96." (PMID 25594563, 2015). "Next, we injected AQP2:Rac1f/f mice with Y-27632 upon reversal of ureteral obstruction [10 mg/kg, intraperitoneally (i.p.), per day for 5 days]." (PMID 38324689, 2024). "Conversely, the inhibition of TNF downstream effector interleukin 1β increases the Aqp2 gene expression under ureteral obstruction conditions." (PMID 35685285, 2022). "In this study, we investigated the AVP-independent regulation of AQP2 by TAM and the therapeutic effect of TAM on the dysregulation of AQP2 and impaired urinary concentration in a unilateral ureteral obstruction (UUO) model." (PMID 31447686, 2019). "Previous studies have shown that AQP2 was significantly downregulated in the kidneys after bilateral as well as unilateral ureteral obstruction injury." (PMID 31447686, 2019). "The urine volume was elevated in the bilateral ureteral obstruction (BUO) animals even though the AQP2 levels appeared to be unchanged relative to sham operated control animals." (PMID 26517129, 2015). "Pharmacological manipulation with angiotensin receptor blockers (e.g. candesartan) 99 or COX-2 inhibitors 100,101 might prevent the reduction in AQP2 down-regulation and post-obstructive polyuria, as seen in animal models of ureteral obstruction." (PMID 25594563, 2015). "Abnormal transcriptional pathways or regulation of mRNA degradation might be involved 96, as AQP2 trafficking to the apical plasma membrane of collecting duct principal cells is still functional after ureteral obstruction 95–97." (PMID 25594563, 2015). "In this study, we investigated the effect of TAM on AQP2 expression and trafficking in the inner medullary collecting duct (IMCD) cells under normal and disease conditions using a unilateral ureteral obstruction (UUO) model, where urinary concentration is impaired." (PMID 31447686, 2019).
renal failure (8 papers, 2010 to 2025). "The ability to concentrate urine was decreased in renal insufficiency due to an impaired and reduced response in c-AMP and AQP2 to AVP, which was elevated in plasma, presumably as a compensatory phenomenon." (PMID 20923561, 2010). "The ability to dilute urine was deteriorated in renal insufficiency, presumably due to both a lack of suppression in AVP during water loading and a defect in the regulatory function of AVP on c-AMP with a secondarily up regulation of AQP2 water channels." (PMID 20923561, 2010).
ischemia (7 papers, 2016 to 2024). A hypoperfusion of the BLOOD through an organ or tissue caused by a PATHOLOGIC CONSTRICTION or obstruction of its BLOOD VESSELS, or an absence of BLOOD CIRCULATION. "In conclusion, the results of this study show a novel effect of rIPeC on the ischemia‐induced control of renal water and sodium excretion, and suggest that regulation of AQP2, pAQP2, and Na–K‐ATPase underlies this effect." (PMID 27405971, 2016). "This was associated with attenuation of the I/R‐induced decrease in urine osmolality, suggesting that rIPeC reduces ischemia‐induced urinary concentration defects by regulating AQP2 and pAQP2." (PMID 27405971, 2016). "The kidney medulla regions have low oxygen tension, and we hypothesize that AQP2 EVs are mainly derived from the medullary regions and are released as a response to ischemia." (PMID 39334890, 2024).
hydronephrosis (6 papers, 2008 to 2021). Collection of urine in the renal pelvis that results in dilatation of the renal pelvis and calyces. "Constitutively elevated plasma tonicity (~400 mOsm/kg) has been reported in mice deficient in V2 vasopressin receptor, and in mice with congenital progressive hydronephrosis caused by a mutation in aquaporin-2." (PMID 18221508, 2008). "Since the AQP2-S256L mutation also prevents phosphorylation at S256 and the subsequent accumulation of AQP2 on the apical membrane of the collecting duct principal cells, mice homozygous for this mutation had severe urine concentration defects and developed congenital progressive hydronephrosis." (PMID 32993088, 2020). "For instance, mutation of Aqp2, a mouse model of nephrogenic diabetes insipidus (NDI), causes polyuria, hydronephrosis and kidney insufficiency." (PMID 27528422, 2016). "Though a decreased number of PCs was previously observed in Adam10 KO mice, leading to polyuria and hydronephrosis and suggesting a role for Aqp2 in mediating the KO phenotype, very different mechanisms affecting cell plasticity may be at play." (PMID 34131651, 2021).
Hypercalciuria (6 papers, 2012 to 2025). "In TRPV5−/− mice, Renkema and coworkers demonstrated that the risk of supersaturation produced by hypercalciuria is attenuated by activation of apical CaR, resulting in reduced AQP2 expression and higher net acid secretion though H+-ATPase." (PMID 22403735, 2012). "Furthermore, hypercalciuria is associated with elevated levels of urinary AQP2 in enuretic children." (PMID 25006961, 2014). "Due to severe hypercalciuria, a tonic activation of the luminal CaSR in the collecting duct is expected in this dKO mice model and, quite interestingly, those mice had a strong reduction in total AQP2 expression associated with a significantly higher expression of AQP2-pS261 and ubiquitinated AQP2." (PMID 31717830, 2019). "Simultaneously, hypercalciuria activates the calcium-sensing receptor (CaSR) in the collecting duct, which inhibits adenylate cyclase and suppresses cAMP-dependent AQP2 trafficking to the apical membrane." (PMID 41393191, 2025). "AQP2 was also reduced in the inner medulla of animal models of hypercalciuria including hypercalciuric rats and TRPV5 null mice." (PMID 25006961, 2014). "Hypercalciuric enuretic children treated with DDAVP and low calcium diet reduced hypercalciuria and this resulted in a reduced overnight urine output and increased nighttime AQP2 excretion and osmolality." (PMID 22403735, 2012). "In another rat model of hypercalciuria, it was demonstrated that the secretion of antidiuretic hormone is reduced, and antidiuretic hormone affects a series of reactions that trigger aquaporin 2 production by binding to V2 receptors in the collecting duct of the renal cortex." (PMID 35323672, 2022). "Interestingly, hypercalciuric enuretic children receiving a low calcium diet to reduce hypercalciuria, had decreased overnight urine output (reduced nocturnal enuresis) paralleled by an increase in nighttime AQP2 excretion and osmolality." (PMID 31717830, 2019). "In the collecting duct principal cells, CaSR is co-expressed with aquaporin-2 (AQP2) on the apical membrane, where it senses extracellular (urinary) Ca2+ and regulates the water reabsorption in order to control hypercalciuria and prevent Ca2+ crystal formation." (PMID 31717830, 2019). "It has been recently suggested that CaSR expressed at the apical membrane of collecting duct principal cells could mediate the effects of hypercalciuria in reducing vasopressin-elicited osmotic water permeability and urinary concentrating ability by the activation of autophagic degradation of AQP2." (PMID 31717830, 2019).
kidney damage (6 papers, 2014 to 2024). "Wuling Decoction promoted AQP2 expression in the nephropathy model group and inhibited AQP2 expression in the diarrhea group." (PMID 35068345, 2022). "They suggest AQP2 in uEV could be used as an early biomarker for drug- induced kidney damage." (PMID 34843700, 2022).
Ascites (5 papers, 2012 to 2021). Accumulation of fluid in the peritoneal cavity (between the layers of the peritoneum that lines the abdomen). "A recent study has also shown that the upregulation of AQP2 in the distal colon was found in cirrhotic rats with ascites, and its expression is inhibited by Tolvaptan, which probably leads to decreased water reabsorption and induces diarrhea in cirrhotic rats with ascites." (PMID 27589719, 2016). "TDEE and its diterpenoids can inhibit the reabsorption and concentration of water in the kidneys by reducing the expression levels of AQP1, AQP2, AQP3 and AQP4, thereby resolving ascites." (PMID 33578967, 2021).
Hypernatremia (5 papers, 2017 to 2021). An abnormally increased sodium concentration in the blood. "A net loss of water due to the insufficient insertion of the AQP2 water channel into the apical membrane of collecting duct cells appears to be a typical condition of hypernatremia." (PMID 34903939, 2021). "Under the condition of hypernatremia and hypovolemia,AVP is released and induces AQP2 expression and translocation from intracellularvesicles to the apical membrane in the renal collecting ducts via theV2 receptor to allow water reabsorption and the maintenance of body-waterhomeostasis." (PMID 29718707, 2018).
Renal cyst (5 papers, 2017 to 2024). A fluid filled sac in the kidney. "The tubular epithelium of renal cysts in Tsc1 KO mice showed a predominant and widespread labeling with H+-ATPase on their apical membrane and a paucity of AQP2 labeled cells." (PMID 38731991, 2024). "Renal cysts also displayed apical membrane domain labelling for AQP2." (PMID 38339183, 2024). "Pde1a mutants had a mild renal cystic disease and a urine concentrating defect (associated with upregulation of PDE4 activity and decreased protein kinase A dependent phosphorylation of aquaporin-2) on a wild-type genetic background and aggravated renal cystic disease on a Pkd2WS25/- background." (PMID 28750036, 2017).
breast carcinoma (4 papers, 2020 to 2023). "Recent studies used public database analysis have found that AQP2 protein is related to the diagnosis and prognosis of breast cancer, ovarian cancer, glioblastoma, and renal cancer." (PMID 36117171, 2022). "Estradiol upregulates AQP1 in prostate cancer; AQP2 in EC; and AQP3 in breast cancer." (PMID 37760476, 2023).
endolymphatic hydrops (4 papers, 2005 to 2024). An accumulation of endolymph in the inner ear (labyrinth) leading to buildup of pressure and distortion of intralabyrinthine structures, such as cochlea and semicircular canals. "Treatment of rats with arginine vasopressin caused a doubling of AQP2 mRNA in the cochlea and endolymphatic sac, and the authors suggested that overexpression of AQP2 might be involved in the formation of endolymphatic hydrops." (PMID 15888206, 2005). "Acupuncture at Baihui (GV20) was observed to reduce the degree of cochlear hydrops in the animal model of AVP-induced endolymphatic hydrops, accompanied by a down-regulation of cochlear AQP2 expression." (PMID 39722819, 2024). "As a consequence, this would negatively interfere with the re-absorption of endolymph AQP2 insures (in part) when needed, which could ultimately lead to endolymphatic hydrops." (PMID 37928160, 2023). "Moxibustion at Tinggong (SI19) has been demonstrated to down-regulate plasma AVP, cochlear AQP2, and aquaporin 7(AQP7) expression in the animal model with endolymphatic hydrops, thereby achieving the effect of intervening in endolymphatic hydrops." (PMID 39722819, 2024). "It was found that in the guinea pig model of AVP-induced endolymphatic hydrops, plasma AVP concentration was increased, cochlear V2R expression was downregulated, and cyclic adenosine monophosphate (cAMP) and aquaporin 2(AQP2) expression were upregulated." (PMID 39722819, 2024).
autosomal dominant polycystic kidney disease (3 papers, 2019 to 2026). Autosomal dominant form of polycystic kidney disease. "In autosomal dominant polycystic kidney disease (ADPKD), high cAMP levels in the renal principal cells contribute to the excessive water retention through a predominant localization of AQP2 in the plasma membrane." (PMID 32164329, 2020).
endometrial carcinoma (3 papers, 2019 to 2022). A malignant tumor arising from the epithelium that lines the cavity of the uterine body. "According to the report of Moon CS, AQP2 is closely related to the invasiveness of endometrial cancer cells." (PMID 36313709, 2022). "ERE can mediate the estrogen-mediated regulation of AQP2 in normal endometrium as well as in endometrial carcinoma cells." (PMID 31447686, 2019). "Interestingly, Zou and co-workers have previously identified a functional ER response element (ERE) in the AQP2 promotor in endometrial carcinoma cells." (PMID 31447686, 2019).
endotoxemia (3 papers, 2012 to 2019). "The higher serum osmolality in AQP1-KO mice during endotoxemia in the absence of water repletion was associated with higher AQP2, AQP3, and Na+-K+-2Cl− cotransporter type 2 expression and a lower Na+/H+ exchanger type 3 protein expression than that in WT mice during endotoxemia." (PMID 31023968, 2019).
glioma (3 papers, 2018 to 2022). A benign or malignant brain and spinal cord tumor that arises from glial cells (astrocytes, oligodendrocytes, ependymal cells). "AQP2 expression was detected in glioma cells, astrocytes, and microglial cell lines, but was rarely expressed in rat BMECs." (PMID 35386692, 2022). "In our study, we conclude that AQP2 was located mainly in the nuclei of the glioma cell lines and is capable of inhibiting cell invasion." (PMID 30345080, 2018). "The experimental results from the present study provide several novel pieces of information regarding the mechanisms of AQP2 function and sublocalization in glioma by E2 and ERs." (PMID 30345080, 2018). "Here, we demonstrate the effects of estrogen on invasion of glioma cells via regulating estrogen nuclear receptors (ERα and ERβ) combined with aquaporin 2 (AQP2)." (PMID 30345080, 2018). "Based on the fluorescent staining (FS) results, we assume that AQP2 is located mainly in the outer part of the nuclei in glial and glioma cells in the tissues." (PMID 30345080, 2018). "Overexpression of AQP2 with the AQP2 vector (pSLLV-CMV-Zsgreen-puro) significantly decreased basal glioma cell invasion." (PMID 30345080, 2018). "Western blot analysis showed that expression levels of AQP2 were decreased in glioma cells compared to that in glial cells from the tissues." (PMID 30345080, 2018). "The expression levels of AQP2 in glioma cells from low-grade tumors (i.e., stages I and II) were lower in glioma cells than those in high-grade tumors (stages III and IV), but there was no statistical difference." (PMID 30345080, 2018). "In short, our findings successfully proved that AQP2 regulation of glioma cell invasion was induced by E2." (PMID 30345080, 2018). "We aimed to investigate AQP2 involvement in estrogen-dependent glioma invasion to gain relevant mechanistic insights into this process." (PMID 30345080, 2018). "The expression of ERα was found to be high, whereas the expression of both ERβ and AQP2 was low in glioma cells from patient tissues and glioblastoma cell lines." (PMID 30345080, 2018). "To investigate the localization of AQP2 in specific cells in the central nervous system (CNS), we explored whether AQP2 was expressed in C6 (glioma cells), rat BMECs (brain microvascular endothelial cells), CTX-TNA2 (astrocytes), and HAPI (microglia) cells." (PMID 35386692, 2022). "However, AQP2 was mainly expressed in the outer part of the nuclei in glial and glioma cells in the tissues." (PMID 30345080, 2018). "There is a lack of direct mechanistic evidence to explain AQP2 regulation of cell migration and invasion of glioma cells." (PMID 30345080, 2018). "This is the precedent of the discovery of AQP2 with differential sublocalization in gliomas, with or without pretreatment with E2." (PMID 30345080, 2018). "There have been no reports regarding AQP2 expression in gliomas." (PMID 30345080, 2018).